PPARA (peroxisome proliferator activated receptor alpha)
Diseases named in the same sentence as PPARA in open-access papers (continued):
Sharing a sentence is not in itself a finding about the gene and the disease.
age-related macular degeneration (8 papers, 2008 to 2024). Age-related loss of vision in the central portion of the retina (macula), secondary to retinal degeneration. "A study reported the PPARα’s anti-apoptotic properties in retinal ischaemia, whilst another demonstrated anti-oxidative and anti-angiogenic effects of PPARα in age-related macular degeneration." (PMID 38993197, 2024). "We also suggest PPARα as a putative therapeutic target for age-related macular degeneration, which may be due in part to decreased mitochondrial efficiency and subsequent energetic deficits." (PMID 29183319, 2017). "In the disease state of age-related macular degeneration (AMD), PPARα activation has also been suggested as a promising therapeutic target." (PMID 34833044, 2021).
amyloid (8 papers, 2015 to 2025). "Taken together, these results demonstrate that curcumin is a PPARα activator and may affect expression levels of proteins involved in amyloid deposition to influence amyloidosis and metabolism in a complex manner." (PMID 33496266, 2021).
Chagas disease (8 papers, 2016 to 2023). A parasitic infection caused by Trypanosoma cruzi. "Taking all this into account, our group has led research on the effect of different PPAR agonists in the context of Chagas disease, that bear in common anti-inflammatory properties besides their effect on carbohydrate (PPARγ) or lipid (PPARα) metabolism." (PMID 33072115, 2020).
chronic lymphocytic leukemia (8 papers, 2017 to 2025). "Moreover, PPARα-mediated FAO has been associated with the aggressiveness of chronic lymphocytic leukemia (CLL), conferring immunosuppression and resistance to metabolic and cytotoxic stress." (PMID 30771209, 2019). "Peroxisome proliferator-activated receptor alpha (PPARA) has been suggested as a therapeutic target for chronic lymphocytic leukemia (CLL)." (PMID 37404899, 2023). "Inhibition of PPARA gene induces immunogenic death of proliferating chronic lymphocytic leukemia cells." (PMID 33390794, 2021). "Similarly, treatment of chronic lymphocytic leukemia (CLL) cells with dexamethasone enhanced FAO by upregulating PPARα, leading to their resistance to dexamethasone." (PMID 40514365, 2025). "Therefore, PPARα antagonist MK886 and NXT629 inhibit chronic lymphocytic leukemia (CLL) cell proliferation." (PMID 28948004, 2017).
experimental autoimmune encephalomyelitis (8 papers, 2008 to 2025). An autoimmune demyelinating disease of the central nervous system that is produced experimentally in animals by the injection of homogenized brain or spinal cord in Freund's adjuvant. "Pparα deficiency leads to enhanced Th17 development in vivo and is associated with enhanced pathology in a murine experimental autoimmune encephalomyelitis (EAE) model." (PMID 37452099, 2023). "In another study, PPARα-KO mice showed increased helper CD4+ T cell type 17 (Th17) generation resulting in increased pathology of murine experimental autoimmune encephalomyelitis." (PMID 38746124, 2024). "In another study, PPARα-KO mice presented increased IL-17A+CD4+ T-cell (Th17) generation, resulting in increased pathological features of murine experimental autoimmune encephalomyelitis (EAE)." (PMID 39910334, 2025). "Although all PPARs ameliorate experimental autoimmune encephalomyelitis (EAE), recent evidence suggests that PPARα, PPARβ/δ agonists have less pronounced immunomodulatory effects and, along with PGC-1α, are not biomarkers of neuroinflammation in contrast to PPARγ." (PMID 30669473, 2019).
Impaired glucose tolerance (8 papers, 2008 to 2025). An abnormal resistance to glucose, i.e., a reduction in the ability to maintain glucose levels in the blood stream within normal limits following oral or intravenous administration of glucose. "PPARα Leu162Val allele has been found to be associated with impaired glucose tolerance and this deleterious effect of PPARα mutation is neutralized by the Ala12 variant." (PMID 19390629, 2009). "Activators of both PPARα and PPARγ have been shown to improve insulin sensitivity and normalize impaired glucose tolerance in both humans and rodent models of IR." (PMID 32290353, 2020). "Many of the effects of TTA in this study point in direction of PPARα as well as PPARδ activation, with a similar pattern of lipid lowering effects as observed in patients with impaired glucose tolerance after treatment with fenofibrate, which is a selective PPARα agonist." (PMID 22190907, 2011). "Data suggest that ERα knockout mice express impaired glucose tolerance and IR, downregulation of peroxisome proliferators-activated receptors (PPAR), PPARα and PPARΔ, and uncoupling protein-2 (UCP2) expression in skeletal muscle as well as elevated inflammatory signaling in liver." (PMID 32029220, 2020).
kidney (8 papers, 2013 to 2024). "In addition to CPTI, the effects of clofibrate on expression of genes PGC1α, MCAD, LCAD, and VLCAD with increased PPARα were reported in the nephrotic kidney in rats." (PMID 31979102, 2020).
lung adenocarcinoma (8 papers, 2009 to 2023). A carcinoma that arises from the lung and is characterized by the presence of malignant glandular epithelial cells. "PPARα mRNA was also increased in Foxm1-depleted A549 lung adenocarcinoma cells in vitro." (PMID 19672312, 2009).
memory impairment (8 papers, 2015 to 2025). "The present study demonstrated the protective effect of PPARα agonist FF on memory impairment after long-term isoflurane anesthesia and identified the role of fatty acid oxidation-related proteins in the process of POCD." (PMID 38023298, 2023). "Several studies have shown that PPARα and PPARγ activation mediates by promoting the regulation of pathologic processes including neuroinflammation, mitochondrial alterations, and memory impairment." (PMID 35899125, 2022). "PPARA agonists were shown to improve autophagy in astrocytes and improve memory impairment in mice." (PMID 40301248, 2025).
breast tumor (7 papers, 2010 to 2023). "The activity scores of the PPARA pathway were calculated for breast tumor samples from TCGA and BC cell lines from GSE48213." (PMID 36424525, 2023). "With the BC cell lines, we were surprised to see that the distribution of the FOXM1 and PPARA pathway activity scores in breast tumor cell lines is similar to that in TCGA breast tumor patients." (PMID 36424525, 2023). "In mammospheres exposed to the breast tumor fibroblasts supernatant, autocrine tumor necrosis factor-α signalling engenders the functional interplay between peroxisome proliferator activated receptor-α and hypoxia inducible factor-1α (PPARα/HIF1α)." (PMID 23372804, 2013). "The similarity of the PPARA pathway activity score in TCGA breast tumor tissue samples and GSE48213 BC cell lines suggests that the compounds that can modulate the PPARA pathway in BC cell lines could also potentially modulate the pathway in breast tumor tissue samples." (PMID 36424525, 2023). "Similarly, the activity of the PPARA pathway does not show significant differences among the three GSE48213 BC cell line subtypes (ANOVA, p-value = 0.15), similar to the results observed in TCGA breast tumor tissue samples." (PMID 36424525, 2023).
Cholestatic liver disease (7 papers, 2018 to 2024). "Activation of PPARα had a beneficial effect on cholestatic liver diseases, and was mainly involved in the inhibition of CYP7A1 and upregulation of CYP3A4, UGT1A, and SULT2A1, and induction of MDR2 to increase biliary phospholipids secretion." (PMID 30774596, 2019). "On the other hand, selective activation of FXR as well as PPARα has beneficial effects on the course of cholestatic liver diseases." (PMID 30100908, 2018). "In particular, PPARα downregulates bile acid synthesis by inhibiting CYP enzymes, e.g., CYP7A1 and CYP27A1, making it a desirable target for the pharmacological treatment of cholestatic liver diseases." (PMID 39120326, 2024). "Importantly, PPARα transactivates several UGT enzymes involved in bile acid glucuronidation, suggesting this nuclear receptor could be a therapeutic target to promote bile acid detoxification to treat cholestatic liver diseases." (PMID 39120326, 2024).
clear cell renal cell carcinoma (7 papers, 2014 to 2024). "Activating the PPARα/CPT1A axis alleviates lipid accumulation and inhibits cell proliferation and migration of clear cell renal cell carcinoma." (PMID 38844980, 2024). "We provide evidence that low ALDH7A1 expression is a useful prognostic marker of poor clinical outcome for hepatocellular and renal clear cell carcinomas and hypothesize that patients with low ALDH7A1 might benefit from therapeutic approaches addressing PPARα activity." (PMID 30486822, 2018).
Crohn disease (7 papers, 2011 to 2024). A gastrointestinal disorder characterized by chronic inflammation involving all layers of the intestinal wall, noncaseating granulomas affecting the intestinal wall and regional lymph nodes, and transmural fibrosis. "Future studies should determine whether PPARα, PPARγ, AMPK, and mTOR modulate glycolysis in Crohn’s disease in an AhR-independent manner." (PMID 36131123, 2022).
Cushing syndrome (7 papers, 2022 to 2025). Cushing's syndrome (CS) encompasses a group of hormonal disorders caused by prolonged and high exposure levels to glucocorticoids that can be of either endogenous (adrenal cortex production) or exogenous (iatrogenic) origin. "In conclusion, these results indicated that m6A-mediated PPARA translational suppression contributes to CORT-induced visceral fat deposition in chickens, which may provide a new target for the treatment of Cushing’s syndrome." (PMID 36555401, 2022).
kidney cancer (7 papers, 2013 to 2024). Primary or metastatic malignant neoplasm involving the kidney. "In kidney cancer, inhibiting PPARA through an antagonist or siRNA could induce apoptosis and cell cycle arrest of kidney cancer cell lines, and it has been proven to be a diagnostic and prognostic marker for ccRCC." (PMID 37201027, 2023). "We also demonstrate that there would be better prospects for kidney cancer when PPARA and TKTL1 are co-treated." (PMID 38675412, 2024). "At the RNA level, CDCA8 was overexpressed, while CDH1 and PPARA were downregulated in kidney cancer tissues, in TCGA-KIRC." (PMID 37201027, 2023). "In our continuing study of kidney cancer using metabolomics methods, we found metabolic signatures of PPARα modulation in a human RCC cell (Caki-1) xenograft model across all three “matrices” (tissue, serum, and urine)." (PMID 23951092, 2013). "So, there would be better prospects for kidney cancer when PPARA and TKTL1 are co-treated." (PMID 38675412, 2024). "In addition, three genes (CDCA8, CDH1, and PPARA) presented as independent factors of kidney cancer by multivariate cox regression." (PMID 37201027, 2023). "Here, we analyzed the SUMOylation-related gene expression status at the RNA level in kidney cancer tissues and built a risk model using three SUMOylation genes, CDH1, CDCA8, and PPARA, to indicate the outcomes based on differentially expressed SUMOylation genes." (PMID 37201027, 2023). "In this regard, it is worth noting that PPARα inhibition by GW6471 was recently reported to attenuate kidney cancer growth in a xenograft mouse model, with no adverse effects in the animals." (PMID 28594934, 2017).
lipodystrophy (7 papers, 2007 to 2024). A congenital or acquired disorder characterized by abnormal loss or redistribution of the adipose tissue in the body. "Using real-time quantitative PCR, we further showed that AT alleviated lipodystrophy-induced activation of hepatic lipogenesis (Pparγ, Fas, and Scd1) and inhibition of triglyceride-rich lipoprotein packaging (Mtp) and fatty acid β-oxidation (Pparα and Cpt1α) in Seipin/Apoe dKO mice." (PMID 38525541, 2024).
renal carcinoma (7 papers, 2009 to 2022). A carcinoma arising from the epithelium of the renal parenchyma or the renal pelvis. "Furthermore, the same research group reported that the PPARα antagonist significantly reduced renal carcinoma growth in xenograft mice and inhibited the enhanced glycolysis, with no adverse effects." (PMID 33525605, 2021). "The authors hypothesized that the transcriptional activity of PPARα was inhibited, which was the reason why the renal carcinoma cells were unable to use FAO by converging on glycolysis to obtain energy." (PMID 29966227, 2018). "As a whole, our data confirm that GW6471 has a cytostatic and cytotoxic effect in GSCs, as in breast and renal cancer cell lines, and suggest that PPARα may control GSCs proliferation and survival." (PMID 29312541, 2017).
sarcopenia (7 papers, 2021 to 2026). Progressive decline in muscle mass due to aging which results in decreased functional capacity of muscles. "Some of these functions have been described also for PPARα, whose decreased expression (possibly explained by decreased levels of its endogenous ligands) has been associated with sarcopenia." (PMID 34854262, 2022). "Altogether, these data indicate that the activity of ESRRs and PPARA, and of their common regulator PGC-1α should be monitored during human aging to identify individuals at risk of sarcopenia." (PMID 33580198, 2021).
skin inflammation (7 papers, 2020 to 2025). "Interestingly, it has been reported that PPARα expression in the skin is reduced in patients with AD and that PPARα-deficient mice develop more severe hapten-induced AD-like dermatitis than wild-type mice." (PMID 37638035, 2023). "This difference in the gene expression patterns of PPARα and PPARβ/δ during the course of dermatitis indicates that PPARβ/δ activation is related to the exacerbation of inflammation." (PMID 36825199, 2023). "An important role in skin homeostasis has likewise been evidenced for the cannabinoid target PPARα, which is a major trigger of skin inflammation." (PMID 36552866, 2022). "Therefore, we provide the first evidence supporting a key role for PPARα/γ activation in the ameliorative effects of CHA on UVB-induced skin inflammation, which include restoring PUFAs homeostasis and inhibiting the p38 MAPK/COX-2 pathway." (PMID 41300477, 2025).
autoimmune myocarditis (6 papers, 2010 to 2024). Autoimmune myocarditis is an autoimmune disease that affects the heart. "A recently study on autoimmune myocarditis reported PPARα may play an important role by regulating IL-6/STAT3 pathway on Th17 cell differentiation which contributes to inflammatory response." (PMID 35414769, 2022). "PPARα inhibits activator protein −1 (AP-1)-dependent genes involved in inflammation and tumor progression and suppresses Th17 cells through modulation of IL-6/STAT3/RORγt signaling in rat models of autoimmune myocarditis." (PMID 38398835, 2024).
brain injury (6 papers, 2008 to 2023). Acute and chronic (see also brain INJURIES, CHRONIC) injuries to the brain, including the cerebral hemispheres, CEREBELLUM, and brain STEM. "For example, there is compelling evidence that activation of PPARα promotes anti-inflammatory and neuroprotective effects in several models of brain trauma." (PMID 29439712, 2018). "In traumatic brain injury, the PPARα agonistfenofibrate appears to represent a highly promising new anti-inflammatorycompound." (PMID 18382619, 2008).
Cachexia (6 papers, 2022 to 2025). Severe weight loss, wasting of muscle, loss of appetite, and general debility related to a chronic disease. "LIF–STAT3 signaling suppresses PPARα to cause lipid imbalance, while fenofibrate restores lipid homeostasis and reduces cachexia, and PPARδ activation enhances oxidative metabolism and muscle endurance." (PMID 41476922, 2025). "Activating PPARα by feeding mice with the diet containing PPARα agonist fenofibrate restored lipid homeostasis in the liver and significantly inhibited cachexia induced by LIF overexpression." (PMID 38245529, 2024). "Blocking the LIF signaling in the liver or re-activating PPARα inhibits LIF overexpression-induced cachexia in mice." (PMID 38245529, 2024). "This study provides mechanistic insights into cachexia and suggests restoring PPARα-dependent hepatic de novo lipogenesis as a potential strategy to treat cachexia." (PMID 38245529, 2024). "We and others have previously found that mice with cachexia have reductions in hepatic fatty acid oxidation and ketone metabolism, arising from inactive PPARα." (PMID 35719965, 2022). "Importantly, during cachexia a concomitant inhibition of adipogenesis takes place, possibly triggered by PPARα." (PMID 38167536, 2024). "Pharmacological activation of PPARα with the agonist fenofibrate restores hepatic lipid homeostasis and mitigates LIF-induced cachexia, underscoring the importance of isoform-specific regulation in maintaining metabolic integrity." (PMID 41476922, 2025). "Activating PPARα by fenofibrate, a PPARα agonist, restores lipid homeostasis in the liver and inhibits LIF-induced cachexia." (PMID 38245529, 2024). "This study demonstrates the systemic effect of LIF on cachexia, and reveals that LIF overexpression disrupts hepatic de novo lipogenesis via the STAT3/PPARα axis as an important underlying mechanism." (PMID 38245529, 2024). "Activating PPARα by the fenofibrate diet significantly increased the expression of PPARα target genes, restored lipid homeostasis in the liver, and more importantly, significantly inhibited LIF overexpression-induced cachexia." (PMID 38245529, 2024). "In this study, we anticipated that the ketogenic diet would activate PPARα, restore ketogenesis, and protect against cachexia; however, this was not the case." (PMID 35719965, 2022). "Our results demonstrate that LIF overexpression downregulates PPARα expression and its target genes involved in lipogenesis, which suggest that LIF overexpression may decrease lipogenesis and disrupt lipid homeostasis in the liver, thereby inducing cachexia." (PMID 38245529, 2024). "Collectively, these results demonstrate that fenofibrate activates PPARα and its downstream targets involved in lipogenesis in the liver to ameliorate the impaired lipid metabolism induced by LIF overexpression in TgLC mice and C26 tumor-bearing mice, which in turn inhibits cachexia development." (PMID 38245529, 2024). "In patients with cachexia due to chronic obstructive pulmonary disease (COPD), PPARA mRNA expression decreased compared to patients with non-cachectic COPD." (PMID 36355178, 2022).
cognitive decline (6 papers, 2020 to 2026). "Activation of PPARA-mediated autophagy could reduce AD-like pathology and cognitive decline in a murine model." (PMID 32948180, 2020).